FOXP3 (forkhead box P3)
Diseases named in the same sentence as FOXP3 in open-access papers (continued):
Sharing a sentence is not in itself a finding about the gene and the disease.
tumor (continued). "In particular, a significant correlation between the numbers of CD4 and CD8 TILs in tumor/stroma was observed, but, those of stromal CD8 TILs correlated with Foxp3." (PMID 36662367, 2023). "On average 2.07% of cells were FOXP3 positive when DKK1 was highly expressed (n = 130), compared to 0.933% in control tumours (n = 57)." (PMID 35924447, 2023). "Successful evasion of the immune response is required for HPV infections, where infiltrating (CD8+, CD4+) T-cells are reduced and regulatory (FoxP3, CD25+) tumor-infiltrated T-cells increase, allowing cervical disease progression." (PMID 37375112, 2023). "Recurrent patients had higher mean protein expression of FoxP3, MAPK-activation markers (BRAF, p38-MAPK) and PI3K/Akt activation (phospho-Akt) within the tumor regions." (PMID 36980587, 2023). "With the changes in the degree of differentiation of tumor cells in CRC tissues, the number of FoxP3+ Tregs, CD163+ TAMs, and CD66b+ TANs cells changed significantly (P < .05)." (PMID 37232465, 2023). "In this study, we collected CRC samples with different levels of differentiation, detected the infiltration of FoxP3+ Tregs, CD66b+ TANs, and CD163+ TAMs, and analyzed the relationship between cell infiltration and tumor cell differentiation." (PMID 37232465, 2023). "In the ICECs regions at baseline, the most abundant markers of immune cells infiltrating the tumor cells were the pan-macrophage (CD68) and dendritic cell (CD11c) markers, whereas the least abundant were markers of Tregs (FOXP3) and active neutrophils (CD66b)." (PMID 37450351, 2023). "The immune checkpoint marker PD-L1 and PD-1 and the marker of tumor microenvironment (CD8, CD4, FoxP3) were analyzed in a relevant number of ecSCC." (PMID 37932810, 2023). "As the equilibrium between different T cell subsets is involved in the final outcome of the tumor immune response, CD8+/CD4+, CD8+/Foxp3+, and Foxp3+/CD4+ ratios were calculated." (PMID 36508123, 2023). "Overall, these global neighborhood observations indicate that the LT is defined by a highly proliferative epithelium, enriched for tumor epithelial-interacting HLA-DR+ cells and CD3+FOXP3+ Tregs." (PMID 37164949, 2023). "Within the tumor infiltrating CD4+ population CD39 expression is found on both conventional T cells and Foxp3+ Tregs." (PMID 37648263, 2023). "The lymphoid biomarker panel depicts CD3+ T cells, CD3+CD8+ cytotoxic T cells, and CD3+FOXP3+ regulatory T cells (Tregs), while the myeloid biomarker panel shows CD68+ macrophages; the tumor cells were stained for PanCK/SOX10." (PMID 36900182, 2023). "From the analysis of the tumor immune microenvironment, effector CD8+ T cells increased, and immunosuppressive cells, including FOXP3+ regulatory T cells (Tregs), myeloid-derived suppressor cells (MDSCs) and CD206+ macrophages (M2), decreased." (PMID 36635683, 2023). "The intricate TME comprises not only tumor cells but also diverse types of immune cells, including CD4+ FOXP3+ Tregs, myeloid‐derived suppressor cells (MDSCs) and tumor‐associated macrophages (TAMs)." (PMID 37818745, 2023). "This study assessed tumor-stromal collagen, tertiary lymphoid structures (TLSs), and TILs, including CD4+ helper T cells, CD8+ cytotoxic T cells, and FOXP3+ regulatory T cells, as TMEs of PDAC." (PMID 37191859, 2023). "As shown, the tumor-infiltrating CD8+ T cells and FOXP3+ T cells were significantly higher in BC with a TN subtype than that with a non-TN subtype." (PMID 37500811, 2023). "Characterized by the co-expression of surface markers CD4, CD25, and FOXP3, Treg was revealed to be correlated with the poor prognosis of RCC probably through assisting the immune escape of tumor cells." (PMID 37305457, 2023). "To characterize immune populations within the tumor microenvironment, we evaluated the expression of CD3, CD4, CD8, FOXP3, and CD68." (PMID 36672477, 2023).
tumor (continued). "We also detected the changes in Treg cells in the subcutaneous tumor-bearing model, and the results showed that LFA-1 knockout decreased the numbers of CD4 + CD25 + Foxp3 + Treg cells in the blood, spleens, and lymph nodes (**P < 0.01, *P < 0.05)." (PMID 37723552, 2023). "In the tumor microenvironment, Tregs (CD4+ FOXP3+ regulatory T cells), formerly known as suppressor T cells, promote cancer immune evasion through the suppression of antitumor T effector responses." (PMID 37828948, 2023). "In concordance with the expression patterns of immune checkpoint molecules, we demonstrated increased expression of immune suppressor markers such as FOXP3, Tim-3, and LAG3 on tumor CD8 T cells and CD11c+ cells with proximity to tumor tissue." (PMID 38044986, 2023). "One of the essential immune cells favouring tumor growth and regulating the immunesurveillance is the CD4+CD25+Foxp3+ Treg cell." (PMID 37056346, 2023). "CD3 T (P = 0.039), FoxP3 T (P = 0.038), and CD3+CD4+ T (P = 0) cells were more abundant in the tumor rim of HACC than in HER2-negative CRC samples." (PMID 37151285, 2023). "In TIGIT+ Treg cells, the expression level of many immunosuppressing marker genes, including Foxp3, Helios, neuropilin-1, CTLA-4, PD-1 and LAG-3, was upregulated, which inhibited the tumor killing function of T cells." (PMID 38110467, 2023). "IL-12 induced tumor-infiltrated CD45+ and proliferative IFN-γ-positive CD8+ T cells and reduced CD4+ FOXP3+ Treg cells." (PMID 36831498, 2023). "T-cell infiltration [CD8+, FOXP3+, and PD1+ cells] and tumor PD-L1 expression was then investigated in RECQL deficient and RECQL proficient IBC." (PMID 38134458, 2023). "In this study, we found that among tumor-infiltrating CD4 T cells, TNFR2 is quite selectively expressed by Foxp3+ Tregs." (PMID 36865537, 2023). "We also identified two clusters of tumor-specific CD4+ T cells, including a population of Tregs expressing the Treg-defining transcriptional factor Foxp3." (PMID 37143122, 2023). "Knockdown of FoxP3 in CCA cells in vitro reduced proliferation and invasiveness, inhibited T cell survival, and reduced IL10 and TGF-β signaling in the tumor microenvironment." (PMID 37324191, 2023). "In the HC_HE compartment, an average of 88.5% of cells in CD8 + clusters belonged to overrepresented clusters within a given tumor (#3, #4, #9, #11, #21), while an average of 81.4% of CD4 + T-cells belonged to CD4 + FOXP3 + (cluster #2)." (PMID 38057799, 2023). "Specifically, the abundance of α-SMA+ CAFs correlated with CD163+ MØs, in addition, we observed significantly positive correlations among α-SMA+ CAFs, CD163+ MØs and anti-tumor immune cells (i.e. CTLA4, FOXP3, CD4 and CD8 T cells)." (PMID 37254126, 2023). "For this purpose, we performed in a collective of OSCC a clinical data collection as well as immunohistochemical staining of some of the most important tumor-infiltrating immune cells, i.e., CD4+, CD8+, and FoxP3+ T-cells as well as CD1a+ DCs." (PMID 37345025, 2023). "In a murine glioma model, CTLA-4 blockade was shown to enhance anti-tumor immunity via improved CD4+ T cell function and resistance to Foxp3+ Tregs." (PMID 36768342, 2023). "Having defined a relationship between DKK1 and Treg signatures in iCCA, we used a tissue microarray to assess the number of FOXP3+ cells in iCCA patient tissue and compared this to DKK1 protein levels from the same tumours." (PMID 35924447, 2023). "To explore the effect of FOXP3 in the transcriptional program of transferred CD8 T cells, we isolated tumor-infiltrating Foxp3UP and mock OT-I cells at day 5 of ACT and analyzed them by RNA sequencing (RNA-seq)." (PMID 36045586, 2023). "Hypoxia induced HIF-1α results in increased expression of FOXP3 in Treg cells and at the same time, also promotes CCL28 in the tumor microenvironment." (PMID 37056346, 2023).
tumor (continued). "This was accompanied by an elevation of CD8+-T cells and M1 TAM, as well a decrease of FOXP3+-Treg cells and M2 TAM in the tumor tissues, implying that WNT5A modulates the immune response to the tumor in a tolerogenic fashion." (PMID 36982422, 2023). "Compared with the adjacent normal tissues, the tumor tissues showed significantly higher CD68/CD3 and FOXP3/CD8 ratios, representing a more immunosuppressive phenotype in PDAC." (PMID 36900182, 2023). "We also analyzed the expression of CD4, CD8, Foxp3+, NKp46, TRAIL, PD-1, VEGF, and TGFβ2 to gain additional insights into the tumor immune microenvironment at both the two weeks after treatment initiation timepoint and the EOS timepoint, respectively." (PMID 37446056, 2023). "In a hypodermic CT26 tumor model, CD4+ Foxp3+ Treg cells are the predominant immunosuppressive cells." (PMID 37152373, 2023). "EZH2 functions as an epigenetic silencer in tumor-infiltrating Treg cells to inhibit the expression of IL-4 and IFN-γ, while enhancing Foxp3 expression and Treg activation." (PMID 37909018, 2023). "Consistently, the rate of tumor-infiltrating immunosuppressive regulatory T cells (Tregs, CD4+Foxp3+) in MTHMS + L group declined obviously in comparison with the other groups." (PMID 37221157, 2023). "In contrast, T cells carrying a TCR found exclusively in the tumour were enriched for exhaustion markers (CTLA4) and regulatory genes (FOXP3, TNFRSF4)." (PMID 38030622, 2023). "FOXP3 overexpression in mature CD8 T cells improves their antitumor efficacy in adoptive T cell therapy, favoring their metabolic adaptation to the tumor microenvironment as well as their recruitment, proliferation, and cytotoxicity within tumors." (PMID 36045586, 2023). "The major subsets of tumor infiltrating lymphocytes (TILs) include CD3+, CD8+, CD4+, and FOXP3+ cells." (PMID 37537787, 2023). "The combination treatment of Abrine and anti-PD-1 antibody has a synergistic effect on suppressing the tumor growth through up-regulating CD4+ or CD8+ T cells, down-regulating the Foxp3+ Treg cells, and inhibiting the expression of IDO1, CD47, and PD-L1." (PMID 37334368, 2023). "Immune checkpoint molecules (PD-1, PD-L1, PD-L2) and immune suppressor markers (Tim-3, FOXP3, LAG3) were all significantly expressed on tumor T-cells as well as co-stimulatory molecules (STING, B7-H3, OX40L, 4-1BB)." (PMID 38044986, 2023). "Tumor tissues from HCC patients were probed with anti-ALDOA, anti-CD68, anti-CD163, anti-CD4 and anti-FOXP3 antibodies." (PMID 36937389, 2023). "In Treg cells, TCF1 deletion has been shown to upregulate Foxp3, IL2Ra (CD25), and TGFβ1, as well as other activation markers, and are superior at suppressing CD8 T cell proliferation and tumor control." (PMID 37552475, 2023). "Foxp3+CD25+CD4+ regulatory T (Treg) cells can suppress the function of cytotoxic T lymphocytes (CTLs), which are crucial for tumor cell recognition and killing." (PMID 37908722, 2023). "Second, only CD3 and CD8 were used for this study; more research is required on other biological markers of tumor cells, such as CD4 and FOXP3." (PMID 36860311, 2023). "There was a slight increasein the proportion of cases with FOXP3 expression in the tumor cells aftertreatment; 32% of cases treated with neoadjuvant ADT and RT showed FOXP3 tumorcell positivity, compared to 17% of untreated cases." (PMID 36880147, 2023). "It has been revealed that up-regulation of miR-146a/b by FOXP3 led to inhibition of IRAK1 and TRAF6 that resulted in suppression of NF-κB and consequently tumor growth inhibition in BC." (PMID 37689738, 2023). "Especially functional FOXP3+ Treg cells can inhibit cytotoxic CD8+ T cells from attacking tumor cells and promote tumor development." (PMID 36739300, 2023). "We describe a unique tumor-infiltrating immune profile with high levels of lymphocytes (CD4, FOXP3) and dendritic cells (CD21, CD1a and CD83) that are valuable prognostic factors in post-NAC TNBC patients." (PMID 36765559, 2023).
tumor (continued). "Pharmacological blockade of A2aR by SCH58261 delayed the tumour growth in the HNSCC mouse model and significantly decreased the population of CD4+Foxp3+ Tregs and enhanced the anti-tumour response of CD8+ T cells." (PMID 36445478, 2023). "CTLA4 is constitutively expressed in Foxp3+ Tregs and CTLA-4-specific antagonistic antibodies not only augment effector T-cell activation but also induce ADCC-mediated depletion of tumor-infiltrating Tregs." (PMID 37928556, 2023). "Cancer development often entails an excess of host immune tolerance generated by regulatory T-cells, also known as "Tregs" (typically CD4 + FoxP3 + T-cells), over effector CD8 + and CD4 + Foxp3- anti-tumor T-cells in the tumor microenvironment." (PMID 38057799, 2023). "FOXP3+CD4+ Tregs mostly exist in the blood, whereas CTLA4+CD4+ Tregs clone and amplify locally within tumors, indicating local clonal expansion of tumor-resident Tregs." (PMID 37187731, 2023). "Simultaneously, STAT3/Foxp3 axis potentially enforced the Tregs function in TME of EC and served as a promising target for the anti‐tumor immunotherapy." (PMID 36226375, 2023). "Immunohistochemical staining targeted various T-cell markers (CD3, CD4, CD8, and FOXP3), T-cell exhaustion markers (TOX and TIGIT), a B-cell marker (CD20), and a neutrophil marker (CD66b) in tumor and tumor-free mucosa from both groups." (PMID 37835436, 2023). "It is worth to mention that in the syngeneic/immunocompetent PCa model a significant change in the tumor-infiltrating immune populations was observed, with a reduction of CD3+ and FOXP3+ T lymphocytes, as well as of neutrophils." (PMID 36872341, 2023). "Histologically, ChAT–GFP+Foxp3+ Treg cells and ChAT–GFP+ Tconv cells accumulated in HCC tissue, in particular at the tumor border, and were also present in immune cell clusters associated with neoplastic hepatocytes." (PMID 37640929, 2023). "It has been reported that FoxP3 is expressed both in CD4+ T regulatory cells and tumor cells, including pancreatic cancer cells, melanoma cells etc.." (PMID 37531206, 2023). "FoxP3+CD4+ regulatory T cells (Tregs) suppress immune responses and their removal enhanced anti-tumor immunity, resulting in tumor regression in mice; therefore, Treg control has become a new target in cancer immunotherapy." (PMID 37729184, 2023). "In the tumor microenvironment, immunosuppressive factors secreted by tumor cells lead to increased frequency of CD4+Foxp3+ Tregs and MDSCs, which creates an immunosuppressive environment that reduces CD8 activity." (PMID 38035069, 2023). "Although the percentages of CD4+ cells were similar in oe-FOSL2 and vector tumour samples, the number of CD4+CD25+ Foxp3+ Tregs was increased in oe-FOSL2 tumours." (PMID 37380804, 2023). "Meanwhile, TGF-β converts naïve CD4+ T cells into Treg cells, limits effector T cell proliferation and function, and augments FoxP3 and CTLA-4 expression, hence facilitating tumor growth and metastasis." (PMID 37868967, 2023). "Meanwhile, CD8+ T cells, CD4+ T cells, CD4+FoxP3+ Tregs, CD4+FoxP3− Teffs, and CD68+ TAMs were analyzed in the total, tumor, and stroma area, respectively." (PMID 37674198, 2023). "used FOXP3-DRT mice and normal mice to establish a head and neck tumour model, and depletion of Tregs using DT targeting resulted in a significant reduction in tumour burden compared to radiotherapy alone." (PMID 38259489, 2023). "Initially, we comprehensively reviewed the densities of CD3+ T cells, CD8+ T cells, FOXP3+ Tregs, and CD68+ macrophages between the paired adjacent normal tissues and the tumor tissues." (PMID 36900182, 2023). "PD-L1, FOXP3, and CD8 expression in either tumor cells or stromal infiltrated immune cells was also analyzed." (PMID 37221583, 2023).
tumor (continued). "The tumor microenvironment (TME) was histologically graded for inflammation phenotype, and changes were assessed in CD8+ cell density, FoxP3+ cell density, CD8+/GZMB+ cell density, HPV16 E6 and E7 transcript levels, PD-L1 and MHC-I presence on tumor cells." (PMID 36867316, 2023). "On the other hand, high frequencies of CD4+TIM-3+, FoxP3+Helios+TIM-3+ Tregs and FoxP3−Helios+TIM-3+ T cells in circulation are associated with longer DFS in CRC patients, suggesting that T cells expressing TIM-3 could be activated cells with improved anti-tumor activities." (PMID 35655158, 2022). "Consistently, we observed a more distinct immune phenotype at S2 tumours with reduced GZMB (granzyme B) and enriched PDCD1 (PD-1), FOXP3 and CTLA4 compared to N or S1 and S3 tumours." (PMID 35301339, 2022). "In HL-bearing humanized mice, chimeric defucosylated anti-CCR4 mAb (KM2760) dramatically boosted the number of tumor-infiltrating NK cells that mediate ADCC and decreased the number of tumor-infiltrating FOXP3-positive Treg cells." (PMID 35222362, 2022). "Neoantigen vaccination was associated with a decrease in the percentage of regulatory T cells (Treg, CD4+CD25+FoxP3+) and, in particular, TIGIT+ Treg in the tumor, likely due to the increased absolute number of tumor-infiltrating CD4 T cells." (PMID 36569934, 2022). "In this study, both, low FoxP3 frequency and high CD8+/FoxP3 frequency ratio in tumor tissue correlated with a longer survival." (PMID 35634289, 2022). "Subclusters with Entpd1 expression were assigned as tumor-specific T cells, including Treg (CD4+Foxp3+), CD8+ effector (Gzmb+Prf1+Ifng+), CD8+ effector memory (Cd44+Cd69+), CD8+ exhausted subclusters (Pdcd1+Lag3+Tigit+Havcr2+)." (PMID 36209176, 2022). "These included genes consistent with pro-inflammatory immune responses (CD27, CD28, CD3e, CD8a, ICOS, ICOSLG, Pax5, TBX, GATA3, HLA-A, TNFSF14, GPR146), but also immune suppressive influences in the tumor immune microenvironment (CTLA-4, FoxP3, PD-1)." (PMID 36698398, 2022). "Using drugs that reduce expression of FOXP3, such as histone acetyltransferase inhibitors or interfering RNA treatments, could reduce the suppressive activity of affected Tregs to alleviate reduced anti-tumor immunity as well as reduce the number of tumors infiltrating Tregs." (PMID 36428581, 2022). "A moderate correlation between frequencies of FoxP3+Helios+ Tregs and CD4+LAG-3+ T cells in in circulation was stronger in advanced tumor stages, compared to early stages (r = −0.146, p = 0.631 [early]; r = 0.478, p = 0.044 [advanced])." (PMID 36146549, 2022). "Foxp3+ TILs were more and CD8+ TILs were less accumulated in metastatic lymph nodes than in the primary tumour (P < 0.01 and P < 0.01, respectively, Wilcoxon signed-rank test)." (PMID 35597869, 2022). "At the same time, FOXP3 can co-activate the formation and function of β-catenin and the TCF4 (transcription factor 4) complex in the nuclei of tumor cells." (PMID 36235242, 2022). "Some responding patients also had increased total tumor infiltrating lymphocytes and an increased ratio of CD8+:FoxP3+ T regulatory cells (Tregs) in the immune infiltrates." (PMID 35790025, 2022). "Tregs, denoted by increased expression of Foxp3, Ctla4, and Tnfrsf4 (CD134), represented 4.5% of sensitive tumor T cells compared to half as many (2.3%) in the resistant populations." (PMID 35924165, 2022). "Previously, we have measured immune cell infiltrates in these MB tumor tissues, including CD3+ T cells, CD4+ T cells, CD8+ T cells, CD20+ B cells, NK cells, FOXP3+ regulatory T cells, and γδT cells." (PMID 34988920, 2022). "Remarkably, we observed that FOXP3+ Treg cells and TREM2+CD163+ macrophages colocalized within the tumor ecosystem by employing multicolor immunofluorescence staining." (PMID 35359989, 2022).